IL6 (interleukin 6)
Diseases named in the same sentence as IL6 in open-access papers (continued):
Sharing a sentence is not in itself a finding about the gene and the disease.
cancer (continued). "The presence of interleukin-6 (IL-6) can skew TAMs towards a pro-tumorigenic M2 phenotype, enhancing their capacity to support cancer cell survival and metastasis." (PMID 39770433, 2024). "More sensitive diagnostic methods of pathological IL-6 synthesis in early stages of cancer would enable early therapeutic intervention in order to ward off the detrimental effects of Il-6." (PMID 39518029, 2024). "In contrast, IL6, CLAR, LY96, and NT5E, were determined to be significant risk factors for eight cancers." (PMID 38627900, 2024). "In the search for new and so far unexplored immunosuppressor mechanisms in cancer, it was found that albumin neo-structures generated by proteolytic fragmentation had immunoregulatory activities such as the stimulation of IL-6 synthesis." (PMID 39518029, 2024). "In the present study, our research has uncovered that GDFT can mitigate postoperative levels of IL-6 and S100B in elderly cancer surgical patients." (PMID 38584828, 2024). "SASP factors such as IL-6 promote chronic sterile inflammation, which is known to promote the initiation and progression of CVDs and support cancer growth and invasiveness." (PMID 38570838, 2024). "IL-6, a multifunctional proinflammatory cytokine, becomes activated in diverse cancer types such as breast, ovarian, and prostate cancer, renal cell carcinoma, along with multiple myeloma, leukemias, and lymphomas." (PMID 38673838, 2024). "For instance, Siltuximab and a novel mAB, HZ-0408b, have shown better IL6 inhibition as an effective therapy in various diseases, including cancers." (PMID 39766086, 2024). "IL6 is a pleiotropic cytokine produced in response to stress and inflammatory stimuli and plays an important role in tumorigenesis and cancer progression." (PMID 38368261, 2024). "Patients with cancer with blood TC levels less than 180 mg/dL had serum interleukin-6 levels much higher than those of their respective counterparts, which were linked to the development and progression of cancer." (PMID 38168969, 2024). "As discussed, IL-6 and IL-17 can have a pleiotropic effect; they display a paradoxical role in cancer, which is context-dependent." (PMID 38279220, 2024). "Lenvatinib initiates its activity via the inactivation of the p38 MAPK/NF-κB pathway, resulting in decreased levels of circulating TNF-α and IL-6, reducing cancer cell migration and invasion, and enhancing M1 polarization of TAMs in a mouse HCC model." (PMID 39796695, 2024). "Cancer cells produce IL-6 and thrombopoietin to exploit protumor impact and induce paraneoplastic thrombocytosis." (PMID 38745688, 2024). "This study aims to evaluate the relationship between serum GDF-15 and IL-6 levels and their impact on immunotherapy response in cancer patients." (PMID 39766045, 2024). "SPP1 and IL6 followed a similar trend, with only elevated detection levels in cancer, suggesting their involvement in colorectal cancer." (PMID 39523395, 2024). "The robust binding affinities observed in the context of RIP interactions with IL-6 underscore the significance of these proteins in targeting cancer-related pathways." (PMID 38801471, 2024). "More CAF-secreted IL-6 is expected to enhance cancer cell migration and EMT-specific activities shortly." (PMID 38244071, 2024). "Other systemic inflammation‐related blood biomarkers and specific cytokines (such as C‐reactive protein, interleukins IL‐6, and IL‐8) are also commonly measured and used to predict clinical outcomes for patients with cancer." (PMID 38775250, 2024). "Ten days after cancer cell inoculation, significantly higher IL6 concentration was observed in mice bearing MOC2 tumors than in mice bearing TC-1 tumors, confirming the bioinformatic results." (PMID 38468260, 2024). "In this study, the expression levels of UCP1 and IL6 upon cancer cachexia were increased in both adipose tissue and adipocytes; however, this effect was reversed by DOE treatment." (PMID 39519503, 2024).
cancer (continued). "The findings revealed that fibroblasts altered their morphology to a myofibroblast-like shape and secreted increased amounts of IL-6 in the presence of cancer cells, potentially modeling the early steps of PDAC evolution." (PMID 38711620, 2024). "Conversely, SPOP overexpression significantly attenuated IL-6-driven enhancements in cancer aggressiveness in T24 cells." (PMID 39479456, 2024). "The expression of blood-borne B2MG, a biomarker for cancer and many inflammatory diseases has been found positively correlated with age, the levels of p16ink4a, IL-1β and IL-6, and the oxidative stress." (PMID 38447216, 2024). "Interleukin‐6 (IL‐6), in particular, is highly associated with PDAC progression, metastasis, mortality and cachexia in both patients and murine cancer models." (PMID 38632714, 2024). "Aberrant regulation of STAT3 phosphorylation induces the expression of a subset of IL-6-dependent genes that would contribute importantly to diseases, involving altered regulation of immunity or cell proliferation and cancer." (PMID 38533493, 2024). "cGAS-STING-dependent IL-6 production contributes to the survival of chromosomally unstable cancers in an IL-6-STAT3 dependent manner, at the same time inhibiting STAT1 signaling, preventing apoptosis and promoting cell survival and growth." (PMID 38660307, 2024). "Pro-survival signaling amidst CIN also increases factors (such as IL6) that can induce a pro-cancer, M2-like phenotype." (PMID 38805560, 2024). "The impact of IL-6IF structures in sera on IL-6 synthesis was further explored in PBMC cultures where cells from healthy donors were exposed to sera from cancer patients or healthy donors." (PMID 39518029, 2024). "Efforts to produce drugs specific for cancer cachexia mechanisms have included blocking IL-6 signaling with monoclonal antibodies (mAb), including Clazakizumab and Tocilizumab (Toci)." (PMID 38254849, 2024). "Elevated circulating levels of 6 cytokines (PD-L1, CXCL10, HGF, CCL2, MIG, and IL-6) were observed in cancer patients compared with that in healthy volunteers." (PMID 38776028, 2024). "CALB2 collaborates with hypoxia to activate iCAFs, which secrete IL6 to upregulate CALB2 expression in cancer cells via STAT3-mediated direct transcription." (PMID 39358777, 2024). "Upon surgical resection, the cancer cells undergo trauma, and such tumor cells can enhance the generation of cytokines and other factors, including IL-6, C-reactive protein (CRP), TNF-α, IL-1β to affect the immune system." (PMID 38566199, 2024). "By controlling a number of cancer-related processes, including apoptosis, proliferation, angiogenesis, invasiveness, metastasis, and metabolism, IL-6 encourages the growth of tumors." (PMID 38803729, 2024). "The authors postulated a potential correlation between different cancer subtypes and the inflammatory adipose microenvironment rich in IL-6 and TNF-alpha, along with heightened levels of IGF-1 observed in obese patients." (PMID 38611106, 2024). "IL-6 has also been reported to regulate cancer cell proliferation through the epidermal growth factor (EGF) and hepatocyte growth factor (HGF) families." (PMID 38510850, 2024). "Various studies examined and evaluated IL-6′s significance in cancer initiation, metastasis, and development." (PMID 38541074, 2024). "Cancer treatments cause injury to the epithelial cells of the oral mucosa, leading to activation of factors such as TNF-α and IL-6, which are pro-inflammatory." (PMID 39456414, 2024). "A study involving patients with cancer (n = 311) identified elevated IL-6 levels in those experiencing CAC (n = 74), accompanied by a significant increase in platelets, and FFA levels." (PMID 38730660, 2024). "The U937-induced cancer aggressiveness were abrogated by the administration of an IL-6 neutralizing antibody." (PMID 39479456, 2024). "Interferon-γ and IL-6 also have a similar effect to TNF-α on lipid metabolism in animal studies of cancer cachexia." (PMID 39114348, 2024).
cancer (continued). "Our study suggests a significant role of IL-6 in the progression of CRC in the sense that there was significantly higher expression in cancerous tumors compared to adenomatous polyps." (PMID 38979413, 2024). "The overexpression of the cytokine IL-6 is known to promote EMT and fibrosis in several inflammatory conditions that predispose to cancer development." (PMID 38904007, 2024). "For instance, IL-6 has been shown to activate cancer stem cells, facilitating cancer growth and metastasis by promoting anti-apoptotic pathways through STAT3 phosphorylation." (PMID 38840908, 2024). "The overexpression of IL-6 can indicate various health complications, such as anastomotic leakage, cancer, and chronic diseases." (PMID 39412695, 2024). "MALAT1 was found to decrease autophagic flux and increase IL-6 by regulating the PTEN/AKT/mTOR and SQSTM1/NF-κB, thereby transforming fibroblasts into cancer-associated fibroblasts to accelerate GC development." (PMID 37588204, 2024). "Cancer cells also overexpress some pro-inflammatory factors, such as IL-6 and tumor necrosis factor α (TNF-α), that can stimulate adipocyte phenotype in a paracrine fashion." (PMID 39040042, 2024). "As observed in our cohort, nutritional interventions can modulate IL-6 levels, specifically, n-3 PUFA can reduce IL-6 levels not only in patients with cancer, but also in middle-aged and older adults." (PMID 38892570, 2024). "When the stress in the host is terminated, IL-6 synthesis stops, but uncontrolled excessive or persistent IL-6 production plays a pathological role in developing various inflammatory diseases and cancers." (PMID 39110194, 2024). "Mechanistically, BCL6 decreases cancer cell expression of pro-inflammatory cytokines and T lymphocyte chemokines such as IL6, IL1F6, and CCL5." (PMID 38956432, 2024). "Blocking of IL‐6 signaling has been discussed as a potential therapeutic strategy for cancers characterized by pathological IL‐6 overproduction." (PMID 38553868, 2024). "Here, CAF-derived IL6 triggered JAK/STAT3 activation in cancer cells, resulting in NOX4 upregulation." (PMID 38453816, 2024). "PBMCs co-cultured with ovarian cancer cells from advanced patients were found to produce significantly more IL-6 compared to PBMCs co-cultured with early-stage cancer cells." (PMID 39518029, 2024). "Secretion of various growth factors and cytokines such as TGF-β, fibroblast growth factor (FGF), PDGF, IL-6, and IL-8 by CAFs promotes cancer cell proliferation." (PMID 38562556, 2024). "Growing evidence suggests that elevated IL-6 levels are strongly correlated with poor prognosis, reduced survival, and increased metastasis in cancer patients." (PMID 39451730, 2024). "The parathyroid hormone-related protein (PTHrP) and interleukin-6 (IL-6), which act as inducers, provoke cancer cachexia." (PMID 39273055, 2024). "TNF-α, particularly, has demonstrated the ability to stimulate keratinocyte proliferation, potentially contributing to cSCC development, while IL-6 and IL-11 can enhance cancer cell survival and migration, thereby bolstering cSCC growth." (PMID 40013270, 2024). "Previous studies have demonstrated that IL-6 is a pivotal cytokine that mediates CAF-cancer cell crosstalk and promotes cancer progression." (PMID 38303024, 2024). "In this section, we highlight mechanisms whereby IL-6 biology can influence a number of these central processes in cancer biology." (PMID 38689325, 2024). "Along with these immune cells, several cytokines are also involved and contribute to HCC formation and progression, such as transforming growth factor-β (TGF- β) for preventing cancer cell apoptosis and interleukin-6 (IL-6) for promoting cell proliferation." (PMID 39456637, 2024). "During cancer cachexia, catabolism is driven by some cytokines, such as IL-6, and tumorigenic factors, such as PTHrP." (PMID 39273055, 2024).
cancer (continued). "While the secretome from MPS1i-treated cancer cells has been found to trigger expression of Arg1 and Il6, both of which are pro-cancer M2-like macrophage markers, our findings suggest that polarization is much more complex." (PMID 38805560, 2024). "Numerous studies have documented that the activation of STAT3 in cancer cells orchestrates the release of various pro-inflammatory cytokines, including IL-6, IL-10, and VEGF." (PMID 39468431, 2024). "Two proteins that regulate the immune system, interleukin-6 and interleukin-8, work together to promote cancer spread when secreted by metastatic cancer cells." (PMID 38848446, 2024). "During cancer initiation, IL-6 functions to proliferate CD8 cells to release cytolytic molecules and maintain lung homeostasis." (PMID 38279220, 2024). "IL-6 is also produced by various cancer cell lines - human ovarian carcinoma cells, esophageal squamous cell carcinoma, cervical adenocarcinoma, and many others - at significantly lower levels than during acute inflammation, but in a constant manner." (PMID 39206193, 2024). "IL-6, in particular, has been identified as a critical mediator in the communication between ASCs and cancer cells, promoting a pro-tumorigenic environment." (PMID 39519109, 2024). "In this study, we demonstrated significantly higher levels of circulating PD-L1, CXCL10, MIG, HGF, CCL-2, and IL-6 in cancer patients compared to normal healthy subjects." (PMID 38776028, 2024). "IL-6 is a multifunctional cytokine that plays a crucial role in the broad biological activity of cancer cells." (PMID 38800384, 2024). "Interleukin-6 (IL-6), a pro-inflammatory cytokine, facilitates cancer development by activating the Janus kinase 2 (JAK2)–signal transducer and activator of transcription 3 (STAT3) pathways." (PMID 38672257, 2024). "The results show that the pathological POSTN with exon 17 from both fibroblasts and cancer significantly increased IL-6 and IL-8 in each other’s cells." (PMID 39272982, 2024). "Previous research has demonstrated that IL-6 and GM-CSF are key signals released by cancer cell-activated CAFs (oral squamous carcinoma-derived fibroblasts) that synergistically induce monocytes to differentiate into M2-like TAMs using a co-culture system." (PMID 39251966, 2024). "Given the multifaceted roles of the IL-6 cytokine family in cancer progression and immunosuppression, various strategies have been developed to target this cytokine family in cancer immunotherapy." (PMID 39421736, 2024). "We identified podoplanin (PDPN)‐positive cancer‐associated fibroblasts, and CD45+ immune cells had the highest levels of IL‐6 and that CD45+ immune cells were the most abundant cell population quantified." (PMID 38632714, 2024). "Although IL-6 secretion from cancer cell lines was barely detectable, that from CAF and NF was significantly higher than that from OSCC cell lines." (PMID 38510850, 2024). "In oral squamous cell carcinoma, M1-like TAMs enhance EMT by increasing the secretion of IL-6, which also induces cancer stem-like transformations by upregulating MMP14 and MME expression in OSCC cells." (PMID 39068459, 2024). "Interleukin-6 (IL-6) is a cytokine secreted by immune cells, cardiomyocytes, and cancer cells; it is essential for controlling the body’s immunological response to inflammation and infections." (PMID 39200115, 2024). "The role of IL-6 is being studied in various cancers; however, its exact mechanism of action in OSCC among the South Indian population has not yet been studied." (PMID 39099925, 2024). "Several lines of evidence illustrate that IL-6 is closely related to a number of cancers, particularly breast, colon, lung, and ovarian cancers." (PMID 38103126, 2024). "Proposed mechanisms for low albumin in cancer patients include the production of inflammatory cytokines like IL-6 and increased vascular permeability, which raises the transcapillary escape rate of albumin, reducing serum levels." (PMID 39385181, 2024).
cancer (continued). "A positive feedback loop is created when cancer cells’ overactive STAT3 signaling pathway increases IL-6 synthesis." (PMID 38397437, 2024). "In various cancers, an association between signal transducer and activator of transcription 3 (STAT3), interleukin 6 (IL6), and epidermal growth factor receptor (EGFR) on PD-L1 expression has been shown in varying degrees." (PMID 38434518, 2024). "While secretome from MPS1i-treated cancer cells has been found to trigger expression of Arg1 and Il6, both of which are pro-cancer M2-like macrophage markers, our findings suggest that polarization is much more complex." (PMID 37066426, 2024). "IL-6 is recognized as a critical growth factor in different types of cancer-related osteolytic bone metastasis." (PMID 38993553, 2024). "For example, adipocyte-released leptin promotes epithelial–mesenchymal transition (EMT) in breast cancer cells by activating the PI3K/AKT signaling pathway, and TNF-α and IL-6 secretion upregulates PD-L1 in cancer cells to promote immune evasion." (PMID 38714880, 2024). "To identify inflammatory HGSC cancers with poor prognosis, we stratified patient ascites samples by IL6 status, which correlates with poor prognosis." (PMID 38451784, 2024). "The endogenous IL-1 produced by cancer cells acts as a growth factor that promotes the synthesis of other cytokines such as IL-6 and TGF-β in a paracrine and autocrine manner." (PMID 38520006, 2024). "IL-6-induced STAT3 signalling in CAFs is implicated in muscle protein breakdown and cachexia, a severe systemic complication of cancer." (PMID 39676864, 2024). "Pathological IL-6 production in chronic inflammation and thereby in cancer is of major importance in poor cancer control." (PMID 39518029, 2024). "High levels of IL-6 exist in patients with various types of cancer and is often reversely correlated with poor survival." (PMID 38482486, 2024). "In turn, IL-6 compromises the integrity of the endothelial barrier, allowing for the extravasation of circulating cancer cells and metastasis formation in the lung." (PMID 38853850, 2024). "Its generation in pathological conditions is characterized by enhanced proteolytic activity such as malignant tumors and chronic inflammation and is in good agreement with the high IL-6 production in these conditions." (PMID 39518029, 2024). "To understand how cancer cells activates NFs, we analyzed the components of the CM from cancer cells and found IL6 and IL8 were highly secreted." (PMID 38320998, 2024). "This is in good agreement with the higher production of IL-6 in autologous PBMC cultures from patients with more advanced cancer stages." (PMID 39518029, 2024). "Monocytes release various pro-inflammatory cytokines, including interleukins IL-1, IL-6, IL-10, and TNF-α, which are linked to reduced survival and a worse prognosis in patients with malignant tumors." (PMID 39493767, 2024). "The more perspective should be their use in combination with other anti-cancer drugs or the development of new blockers preventing interactions of IL-6 with the receptor complex." (PMID 38715108, 2024). "The interaction between fibroblasts and cancer cells induces an upregulation of neoplastic Osteopontin expression through IL‐6 stimulation, thereby facilitating the growth, migration, and invasion of cancer cells." (PMID 38946720, 2024). "Analyses of altered genes of these specific pathways highlight the significance of IL-6 and IL-8, which are pivotal in cancer biology." (PMID 39336151, 2024). "Collectively, these findings strongly indicate that ITGα5, packaged by specific cancer-derived EVPs, induces vascular permeability through the activation of IL-6 signaling and secretion from IMs." (PMID 38853850, 2024). "Chronic inflammation upregulates several proinflammatory cytokines, mainly IL-1, TNF-α, IFN-γ, IL-6, IL-12, IL-23, and IL-17, involved in both the initiation and progression of cancer." (PMID 38256080, 2024).